IFNG (interferon gamma)
Diseases named in the same sentence as IFNG in open-access papers (continued):
Sharing a sentence is not in itself a finding about the gene and the disease.
melanoma (continued). "Monocyte-derived DCs obtained from peripheral blood of melanoma patients were demonstrated to upregulate IDO expression upon in vitro activation by CD40L and IFNγ." (PMID 33072086, 2020). "In the KEYNOTE-001 study, six gene signatures of INFG-related genes (IDO1, HLA-DRA, STAT1, CXCL9, IFNG and CXCL10) were previously developed in melanoma patients." (PMID 32107458, 2020). "The relationship between senescence signalling and BRAF inhibitor resistance is best exemplified in melanoma where drug resistance is also typically accompanied by dedifferentiation markers such as NGFR, which is inducible by type II interferons (IFNγ)." (PMID 30850015, 2019). "We observed strong Pearson correlation coefficients between IL32 expression, found within the melanoma tumor and the surrounding microenvironment, and genes related to immune cell infiltration, such as CD3E (0.94), CD8A (0.89), IFNγ (0.75), and GZMB (0.86)." (PMID 30953519, 2019). "Consistently, blocking IFNγ by anti-IFNγ antibody increased tumor growth of both control and B16F10 melanoma cells with FTO knockdown in C57BL/6 mice." (PMID 31239444, 2019). "We also evaluated the impact of proinflammatory molecules TNFα and IFNγ on IL32 expression and dedifferentiation in melanoma cell lines in vitro." (PMID 30953519, 2019). "We found that TNFα and IFNγ, which promote a dedifferentiated melanoma phenotype, also induce IL32 expression in non-IL32 expressing melanoma cell lines by impacting activity at the promoter level." (PMID 30953519, 2019). "As seen in a melanoma mouse model, tumor-derived lactic acid also prevents NFAT upregulation, leading to diminish IFNγ production." (PMID 30917934, 2019). "We selected these three melanoma cell lines to observe the parallel impact of TNFα and IFNγ on IL32 and the melanoma differentiation state because they exhibited a low AXL/high MITF differentiated genetic signature." (PMID 30953519, 2019). "We noted that IFNγ stimulated the expression of HLA-ABC, HLA-DR, NGFR, PD-L1, and/or PD-L2 in the majority of melanoma cell lines." (PMID 29977240, 2018). "Serial immune analysis completed on 10 melanoma patients demonstrated CD4 and CD8 T cell responses against 58% of vaccine peptides as measured by via IFNγ ELISpot." (PMID 30400822, 2018). "The remaining 23 melanoma cell lines, including the IFNGR1-mutant D22M1 cells, showed minimal cell cycle profile changes when exposed to IFNγ." (PMID 29977240, 2018). "S4428z-equipped T-cells secreted significant amounts of IFNγ, IL2, and TNFα when cocultured with cells from the primary melanoma culture M#3 (e.g., 3,987, 343, and 1,027 pg/ml, respectively), underscoring the potential clinical relevance of our approach." (PMID 29085357, 2017). "Gene expression analysis revealed top pathways (T cell trafficking, communication, and differentiation) and top upstream regulators (CD3, CD28, IFNG, and STAT3) that significantly changed with age in 84 IMCG and 43 TCGA primary melanomas." (PMID 27760559, 2016). "In melanoma, through homophilic interactions, CEACAM1 inhibits natural killer (NK) cell activity and effector functions (such as cytotoxicity and interferon gamma (IFNγ) release) of tumor-infiltrating lymphocytes (TILs)." (PMID 27642217, 2016). "These melanoma cells were incubated +/− IFNγ, and the ability of NY-ESO-1 specific HLA-Cw3 restricted T-lymphocytes to recognize or kill melanoma cells lines was assessed." (PMID 26885372, 2016). "To determine the effect of constitutive- versus immuno- proteasome processing on antigen presentation by melanoma cells, we selected HLA-Cw3+, NY-ESO-1 expressing cell lines and induced IP expression in each by incubation with IFNγ." (PMID 26885372, 2016). "Reduced frequencies of CD4+IFNγ+ T cells (Th1) and CD8+IFNγ+ T cells (Tc1) were found in melanoma patients at pre-vaccination as compared to healthy donors (p = 0.0005 and p = 0.001, respectively)." (PMID 26176858, 2015).
melanoma (continued). "FL-melanoma and ISRE/FL-melanoma cells were incubated with supernatants from either EGFP-ADSCs or IFNγ-ADSCs for 48 hours." (PMID 25428727, 2014). "They observed 45% relapse-free survival in stage III melanoma patients compared to historical controls, stage III patients from an ECOG IFNγ+ resection study and an ECOG resection only study, which showed 34% and 22%, respectively." (PMID 24949488, 2014). "In this study, we evaluated the therapeutic potential of PhiC31 (φC31) recombinase and/or piggyBac transposase (pBt) modified ADSCs expressing either TRAIL, IFNγ, or co-expressing TRAIL/IFNγ in mouse models of melanoma." (PMID 25428727, 2014). "TCR-5, -9 and -11 mediated IFNg release by transduced lymphocytes when cultured in presence of HLA-A*0201-positive SSX2-positive tumor cells from glioma and melanoma." (PMID 24681846, 2014). "T-cell responsiveness towards native MC2-positive, HLA-A2-positive melanoma cells (i.e., EB81-MEL-2 cells) was enhanced by IFNγ pretreatment, which promotes antigen processing and surface expression of MHC and adhesion molecules." (PMID 22400038, 2012). "TCR T cells killed and produced IFNγ and TNFα upon coculture not only with MC2 peptide-pulsed HLA-A2-positive target cells but also native MC2-positive, HLA-A2-positive melanoma cells." (PMID 22400038, 2012). "The expression of WSX1 in Lewis Lung Carcinoma (LLC) and the melanoma cell line AGS induces the death of T cells and inhibits the production of the effector cytokine IFNγ from NK and T cells, resulting in the promotion of tumor growth." (PMID 21559505, 2011). "TIL pass the screening process, if IFNγ secretion exceeds 200 pg/ml and double the level of a control in which the TIL are coincubated with any HLA-mismatched melanoma cell line." (PMID 21234353, 2010). "HLA-A2 (A*0201) tetramer assay specific for gp100209(210M) and MART-126–35(27L), IFNγ real time RT-PCR and ELISPOT methods were validated using tumor infiltrating lymphocyte cell lines (TIL) isolated from HLA-A2 melanoma patients." (PMID 18945350, 2008). "Further, Qu Spez-educated DC stimulated CD4+T cells in a allogeneic mixed lymphocyte reaction and activated melanoma antigen Melan-A/MART-1-specific M77-80 CD8+T cells as evidenced by increased secretion of TNF-α and IFNγ." (PMID 18533025, 2008). "A positive IFNγ response (by RT-PCR and ELISPOT) to gp100 was demonstrated in PBMC from 3 melanoma patients." (PMID 18945350, 2008). "The ligand of PD1, PDL1, is induced on melanoma cells in response to interferon gamma (IFNG), thereby activating a negative feedback loop that inhibits tumor-specific T cells." (PMID 41432764, 2025). "Additionally, anti-IL-20R2 treatment reduced the expression of IFNγ, GZMB, IL-2, and TNFα in Jurkat cells co-cultured with Vin-treated melanoma cells." (PMID 40866941, 2025). "In melanoma, NOX2 knockout or inhibitor could increase the IFNγ-producing NK cell infiltration into lungs with reduced melanoma metastasis." (PMID 40847302, 2025). "However, melanoma cells adapt during co‐culture by upregulating CIITA and MHC II in response to interferon gamma (IFNγ), thereby evading NK‐cell lysis." (PMID 41078003, 2025). "In B16F10 melanoma mouse models, SON-1210 demonstrated superior efficacy compared to native cytokines, significantly reducing tumor growth and enhancing immune responses, including elevated IFNγ levels and increased Th1 and CTL cell counts." (PMID 40636453, 2025). "To test if DMF treatment is IFNγ‐specific, we determined MHC II expression and NKmK in melanoma cells that were not treated with IFNγ or exposed to NK‐cell co‐culture." (PMID 41078003, 2025). "The production of tumor necrosis factor (TNF) and interferon gamma (IFNγ) in TEX cells upon MCT11-blockade did not improve in the poorly responding melanoma model." (PMID 40114716, 2025).
melanoma (continued). "Our previous studies showed that nNOS inhibitors reduced the expression of programmed death-ligand 1 (PD-L1) in the presence of interferon-gamma (IFN-γ), which is a known pro-tumorigenic cytokine stimulating melanoma progression observed in earlier clinical trials and animal studies." (PMID 40574005, 2025). "In murine melanoma models, the combination of zVAD-fmk with multimodal therapies has been shown to significantly reduce tumor growth, decrease regulatory T cell infiltration, and promote the recruitment of CD8+ T cells along with enhanced IFNγ expression." (PMID 41235238, 2025). "Interferon‐gamma (IFN‐γ), produced by T or NK lymphocytes, is a major cytokine that induces PD‐L1 expression through activating the JAK/STAT signalling pathway, as demonstrated in canine melanoma cells." (PMID 39789732, 2025). "We exposed T cells harvested from treated or mock-infected (control) mice to melanoma [B16F10-OVA] cells and observed substantially increased interferon-gamma (IFN-γ) production, indicating that infection with WE-CL13-GP181M-185W-492I promotes anti-tumoral T cell immunity and tumor control." (PMID 41086811, 2025). "The phenomenon of immune sensitisation following IFNγ-signalling ablation is not restricted to B16F10 melanoma, as other groups have reported similar findings in mammary, colon, pancreatic and lung tumour models in both Balb/c and C57Bl/6 animals." (PMID 39746898, 2025). "IFNγ/STAT1 signaling is known to be both a crucial player in anti-tumoral immune responses as well as a strong activator of immunosuppressive IDO1 expression, particularly in melanoma." (PMID 39962447, 2025). "To do that, we induced dedifferentiation in 624Mel melanoma cells via siRNA mediated MITF knockdown and treated the cells with IFNγ and then performed bulk RNA sequencing on both differentiated (siCTRL) and dedifferentiated (siMITF) 624Mel cells, with or without IFNγ treatment." (PMID 39736644, 2024). "Our team also recently performed a multi-omic analysis of a large, real-world melanoma cohort, detecting in MBM a reduced expression of interferon-gamma (IFNγ) and T cell-inflamed signatures when compared to primary cutaneous melanoma (PCM) or extracranial metastases (ECM)." (PMID 39516255, 2024). "Given its identification as a key regulator in mesenchymal stem cells (MSCs), where it suppresses IFNγ signaling and considering its emerging role in cancer biology, we investigated the function of lncRNA GRASLND in the context of melanoma." (PMID 39398277, 2024). "Expresses interferon-gamma (IFN-γ) fused to the N-terminal region of SipB, allowing for the efficient secretion of IFN-γ from the bacterium and enhancing the localized delivery of IFN-γ for improved melanoma cells cancer treatment outcomes." (PMID 38543481, 2024). "For instance, in a murine model of transplanted melanoma, prophylactic application of TLR4/9 agonists (before tumor inoculation) can activate the IFNγ/STAT1 signaling pathway, promoting tumor cell autophagy and autophagy-related tumor cell death, subsequently reducing metastasis." (PMID 38523155, 2024). "In clinical melanoma, CD4+ Th1/IFNγ was found as the biomarker of better prognosis." (PMID 38827732, 2024). "Human melanoma cells have been demonstrated to be capable of producing CXCL10, which can be induced by some tumor microenvironmental stimuli, such as IFNγ and toll-like receptor (TLR) agonists." (PMID 39268223, 2024). "In accordance with our findings, TIM-3 expression on NK cells has been associated with reduced NK activity in both lung adenocarcinoma and melanoma settings, while TIM-3 levels have been correlated with enhanced IFNγ expression and NK cell cytotoxicity in acute myeloid leukemia." (PMID 39513882, 2024). "Moreover, there is a strongly positive correlation between the expression of IFNG and CD86 in melanoma tissues." (PMID 38491004, 2024).
melanoma (continued). "Treatment of T1185B melanoma cells with IFNγ or the proteasome inhibitor MG132 did not alter differently the presentation of PC and circRNA-BSJ derived peptides, suggesting they follow similar routes of antigen processing and presentation." (PMID 38490980, 2024). "Combination of anti-CTLA4 and anti-PD1 antibodies were effective in melanoma, renal cell carcinoma, and microsatellite instability-high (MSI-H) colorectal cancers, and concomitant blockade of CTLA4 and PD1 increased production of IFNγ from CD8+ cells." (PMID 39095793, 2024). "Our results show that all constructs lead to target cell killing and interferon-gamma (IFNγ) release upon co-culture with melanoma cells with high expression of total TYRP1 but not when co-cultured with cells with intermediate expression." (PMID 38336975, 2024). "Our previous work demonstrated that RNAi-mediated Notch1 inhibition promoted an inflamed TME by reducing immunosuppressive cytokines and factors (e.g., IL10, TGFβ, ARG1), immunosuppressive cells (MDSCs and Tregs); and by increasing IFNγ and CD8+ T cells in the melanoma TME." (PMID 39491031, 2024). "The role of SLFN11 in IFNγ mediated toxicity seems to be context-dependent because SLFN11 was shown to be required for IFNγ mediated toxicity in HAP1 cells but not in prostate or melanoma cell lines." (PMID 38791884, 2024). "Furthermore, reactivated T cells release high levels of interferon-gamma (IFN-γ) to suppress the SLC7A11-GSH-GPX4 axis, thus facilitating the ferroptosis of melanoma cells." (PMID 38216595, 2024). "Bioinformatic analysis of publicly available RNA sequencing data, consisting of 45 patient derived melanoma cell lines, with or without IFNγ treatment, was conducted to assess the generalizability of the in vitro results." (PMID 39736644, 2024). "Publicly available RNA sequencing data (GSE154996) consisting of 45 patient derived melanoma cell lines, either with or without 6-h treatment with 5 ng/mL IFNγ." (PMID 39736644, 2024). "The limited responses to ICB in patients with cancer, including those with B cell lymphoma and melanoma, are largely attributed to the lack of IFNγ production required for the activation of CD8+ T cells." (PMID 39618825, 2024). "In all cases, IFNγ significantly induced NAMPT expression in mouse and human melanoma cells." (PMID 36900204, 2023). "In this study, we found that IFNγ induces NAMPT in both human and mouse melanoma cells." (PMID 36900204, 2023). "The importance of MHC-I was validated by examining autologous CD8+ T cell activation (IFNγ+/CD107+ CD8+ T cells) in the presence or absence of MHC-I blocking antibody in co-culture experiments with two MHC-I positive melanoma cell models." (PMID 36934113, 2023). "Furthermore, the vast majority of primary melanoma cell cultures from ICBT-progressing primary lesions responded robustly to IFNγ7, as did all the cell lines used in our study, suggesting that IFNγ signalling is preserved despite immunoediting." (PMID 37752135, 2023). "IFNγ and IL2 expression in PBMC of healthy dogs in response to rNDV-infected melanoma cells." (PMID 37022566, 2023). "Our data elucidates a mechanism by which IFNγ upregulates NAMPT in both human and mouse melanoma cells by inducing the signal transducer and activator of transcription 1 (STAT1) transactivation via a conserved enhancer that we recently identified in tumor-associated macrophages." (PMID 36900204, 2023). "IFNγ alone or single fatty acids failed to induce cell death in the two mouse melanoma lines Yumm5.2 and B16F10 and the human melanoma line A375." (PMID 37746665, 2023). "Whencombined with immune cells in vitro and ina mouse model of melanoma in vivo, local supplementationof IFNγ via codelivery was not required for effective inductionof MHC expression and strong antitumor immunity." (PMID 37797944, 2023).
melanoma (continued). "They observed that differences in the levels of MITF and Interferon-gamma (IFN-γ) led to innate resistant melanoma cell subpopulations MITF (Extremelyhi) and MITF (low) cell subsets have two types of melanoma cells that present different characteristics and responses to therapy." (PMID 37174106, 2023). "Collectively, these results confirm that the ability of PTP 9 to sensitize cancer cells to the effects of IFNγ and TNFα are not restricted to melanoma cells but extend to other solid tumors, many of which exhibit resistance to ICI therapy." (PMID 36968224, 2023). "Similarly, in melanoma, FTO knockdown increased tumor cell sensitivity to anti-PD-1 treatment by IFNγ in mice." (PMID 36960074, 2023). "In addition, the mean fluorescence intensity (MFI) of CTV was highest in the IFNγ/FK866 combination-treated cells, further suggesting that the combination treatment had the greatest reduction in melanoma cell proliferation." (PMID 36900204, 2023). "In particular, gene expression profiling of B16-F10 melanoma cells reveals that mangiferin selectively inhibits expression, among others, of IL6, TNF, IFNG, VEGFR2, MMP19 and FGF1 genes with consequent deregulation of angiogenesis, cell viability and metastatic processes." (PMID 36768978, 2023). "We next investigated the cytokine profile of ILCs within the melanoma TME and found that blocking PD-1 significantly increased the frequency of ILCs that could express dual effector cytokines such as IL-17 and IFNγ." (PMID 37098069, 2023). "Although HLA-E is either absent or just weakly expressed in melanoma, the presence of NK cells followed by a high Interferon-gamma response is likely what increases HLA-E in melanoma cells." (PMID 38057843, 2023). "Consequently, induction of PARP14 mRNA mirrored IFNG and STAT1 mRNA in on-treatment melanoma biopsies." (PMID 37752135, 2023). "In addition, the mRNA abundance of PARP14 in both melanoma cells and patient samples (TCGA SKCM) positively correlated with that of STAT1, IFNG, and CD274." (PMID 37752135, 2023). "These in vitro results demonstrated that IFNγ sensitizes IFN-responsive melanoma cells towards TNF-induced cell death and suggested that myeloid cell-derived nitric oxide contributes to efficient inflammatory cell death of IFN-unresponsive melanoma cells." (PMID 37316667, 2023). "Alternatively, 105 untransfected DCs were cultured with peptide pools (5μg/ml) from VSV, hTERT (melanoma antigen), Cyclin D1 (melanoma antigen), or the peptide SIINFEKL (irrelevant antigen) for 24 hours and then 106 purified CD8+ T cells were added in interferon gamma ELISPOT wells." (PMID 38022659, 2023). "The remaining 21 PD1 PROG melanoma cell lines responded to IFNγ exposure, and six of these cell lines (6/21; 29%; 4 innate resistant) displayed intrinsic IFNγ signaling in the absence of exogenous IFNγ." (PMID 36934113, 2023). "The diversity of our melanoma cell line panel also led to the discovery of some IFNγ-sensitive lines that were not rescued by ulixertinib exposure (e.g., M230)." (PMID 37803324, 2023). "We used the ERK inhibitor ulixertinib at a concentration of 50 nM, which efficiently blocked growth inhibition in the drug screen but did not affect melanoma cell growth in the absence of IFNγ." (PMID 37803324, 2023). "Improved survival in the prophylactic model could be due to EVs inducing T cells to secrete IFNγ, thereby leading to upregulation of MHC class I expression on melanoma cells." (PMID 36546872, 2023). "In our ELISpot assays, we showed that neither hsa‐miR‐320a‐3p‐ nor hsa‐miR‐200c‐3p‐transfected melanoma cells led to an increased T cell IFNγ secretion, suggesting that a possible PD‐L1 downregulation is probably not the cause of the increased cytotoxicity." (PMID 36718025, 2023). "A 10-gene IFNγ signature predicts response to ICB in melanoma and separates responders from non-responders to pembrolizumab (anti-PD1 antibody) in patients with melanoma." (PMID 36588164, 2023).